SRGAP2 (SLIT-ROBO Rho GTPase activating protein 2)
Description:
Postsynaptic RAC1 GTPase activating protein (GAP) that plays a key role in neuronal morphogenesis and migration mainly during development of the cerebral cortex. Regulates excitatory and inhibitory synapse maturation and density in cortical pyramidal neurons. SRGAP2/SRGAP2A limits excitatory and inhibitory synapse density through its RAC1-specific GTPase activating activity, while it promotes maturation of both excitatory and inhibitory synapses through its ability to bind to the postsynaptic scaffolding protein HOMER1 at excitatory synapses, and the postsynaptic protein GPHN at inhibitory synapses (By similarity). Mechanistically, acts by binding and deforming membranes, thereby regulating actin dynamics to regulate cell migration and differentiation. Promotes cell repulsion and contact inhibition of locomotion: localizes to protrusions with curved edges and controls the duration of RAC1 activity in contact protrusions (By similarity). In non-neuronal cells, may also play a role in cell migration by regulating the formation of lamellipodia and filopodia.
Synonyms: ARHGAP34; FNBP2; KIAA0456; SRGAP2A
Tractability: Small molecule: a structure with a bound ligand is known. Antibody: UniProt places it where antibodies can reach, with high confidence; its Gene Ontology location is reachable by antibodies, with high confidence. PROTAC: ubiquitination databases record sites on it; its protein half-life has been measured.
Gene: Protein-coding gene on chromosome 1 (206,203,346 to 206,464,436, forward strand). Ensembl gene ENSG00000266028.
Subcellular location: Cell membrane; Cell projection, dendritic spine; Postsynaptic density; Postsynaptic cell membrane; Cell projection, lamellipodium; Cytoplasmic vesicle, phagosome; Nucleus; Cytoplasm, cytosol
Subcellular location (Human Protein Atlas): Cytosol; Basal body; Centrosome
Pathways (Reactome):
Signal Transduction: CDC42 GTPase cycle; RAC1 GTPase cycle; RAC3 GTPase cycle; RHO GTPases Activate Formins; RHOF GTPase cycle; RHOQ GTPase cycle; RHOU GTPase cycle
Developmental Biology: Inactivation of CDC42 and RAC1
Gene Ontology:
Molecular function: GTPase activator activity; identical protein binding; protein binding; protein homodimerization activity; small GTPase binding
Biological process: actin filament severing; dendritic spine development; excitatory synapse assembly; filopodium assembly; inhibitory synapse assembly; lamellipodium assembly involved in ameboidal cell migration; negative regulation of neuron migration; positive regulation of GTPase activity; substrate adhesion-dependent cell spreading; extension of a leading process involved in cell motility in cerebral cortex radial glia guided migration; negative regulation of cell migration; nervous system development; neuron projection morphogenesis; regulation of small GTPase mediated signal transduction; regulation of synapse assembly; signal transduction
Cellular component: dendritic spine head; lamellipodium; plasma membrane; cytosol; dendritic spine; glutamatergic synapse; nucleus; phagocytic vesicle; postsynaptic density; postsynaptic membrane
Genetic constraint (gnomAD): Loss-of-function variants: 0 observed, 5.38 expected, observed/expected ratio (o/e) 0, 90% interval 0 to 0.56. That is too few expected variants to judge how well the gene tolerates losing a copy. Missense variants: 9 observed, 50.72 expected, observed/expected ratio (o/e) 0.18, 90% interval 0.11 to 0.31. Synonymous variants: 8 observed, 14.44 expected, observed/expected ratio (o/e) 0.55, 90% interval 0.32 to 1.
Homologues: Orthologues: chimpanzee SRGAP2 (100% identical), macaque SRGAP2 (99% identical), mouse Srgap2 (98% identical), rat Srgap2 (98% identical), dog SRGAP2 (96% identical), zebrafish srgap2 (77% identical), tropical clawed frog srgap2 (75% identical), Caenorhabditis elegans srgp-1 (27% identical). Paralogues in human: SRGAP1 (68% identical), SRGAP3 (60% identical), SRGAP2B (42% identical), SRGAP2C (42% identical), ARHGAP4 (38% identical).
Diseases named in the same sentence as SRGAP2 in open-access papers:
SRGAP2 is named in the same sentence as 30 diseases in open-access papers, as found by Europe PMC text mining. Sharing a sentence is not in itself a finding about the gene and the disease. The quoted sentences say what the papers report.
breast carcinoma (4 papers, 2011 to 2024). "Since pseudopodia formation determines cell migration and invasion, we further investigated srGAP2 tension in human breast cancer cells MCF7 (barely invasive) and MDA-MB-231 cells (highly invasive)." (PMID 36593959, 2023). "SRGAP2 was also involved in breast cancer cell migration and the cancer process." (PMID 39770537, 2024). "Targeting the srGAP2-related physicochemical signaling could be developed into the therapeutic strategies of inhibiting breast cancer cell invasion and durotaxis." (PMID 36593959, 2023). "In human breast cancer tissue samples, co-IP assay showed strong binding of srGAP2 and PKCα." (PMID 36593959, 2023). "However, the exact mechanism of the SRGAP2 in the development of breast cancer still needs further investigation." (PMID 21738711, 2011). "Kaplan–Meier OS analysis of breast cancer patients revealed that low expression of FBXW7, SRGAP2, MTMR3 as well as CDC42, the partner of CDC42BPA, is associated with poor prognosis." (PMID 37463901, 2023). "To further verify whether the SDC4-PKCα pathway regulates srGAP2 phosphorylation and tension in vivo, we investigated SDC4 binding to PKCα in the fresh human breast cancer tissues and adjacent tissues." (PMID 36593959, 2023).
osteosarcoma (3 papers, 2016 to 2022). A usually aggressive malignant bone-forming mesenchymal neoplasm, predominantly affecting adolescents and young adults. "In contrast, SRGAP2 expression is downregulated in osteosarcoma and linked to an aggressive phenotype of that disease." (PMID 36277474, 2022). "SRGAP2 and other axon guidance proteins likely play a role in osteosarcoma metastasis, with loss of SRGAP2 contributing to a more aggressive phenotype." (PMID 27966608, 2016). "SRGAP2 and other axon guidance proteins likely play a role in osteosarcoma metastasis, with loss of SRGAP2 potentially contributing to a more aggressive phenotype." (PMID 27966608, 2016). "While SRGAP2 is described as an oncogenic gene in hepatocellular carcinoma, it functions a metastasis suppressor in osteosarcoma." (PMID 36277474, 2022). "A forward genetic screen utilizing Sleeping Beauty mutagenesis in mice previously identified potential genetic drivers of osteosarcoma metastasis, including Slit-Robo GTPase-Activating Protein 2 (Srgap2)." (PMID 27966608, 2016). "The percent of primary tumors with an insertion in Srgap2 ranged from 13.5% in osteosarcoma to 30% in chronic myeloid leukemia." (PMID 27966608, 2016). "In this work, the overexpression of SRGAP2 also slowed cellular migration in murine osteosarcoma cell lines and the knockout of Srgap2 increased cellular migration in the K12 cell line." (PMID 27966608, 2016). "On average the SRGAP2C: SRGAP2 expression ratio was similar among osteoblasts, primary osteosarcoma samples, and metastatic osteosarcoma samples." (PMID 27966608, 2016). "Transposon insertions were found in Srgap2, Enah, Slit2, Slit3, or Robo1 in 24 percent of primary tumors from mice with Sleeping Beauty derived osteosarcoma, further implicating the role of the Slit-Robo pathway in osteosarcoma." (PMID 27966608, 2016). "To functionally evaluate the potential role of Srgap2 in osteosarcoma development and metastasis, we overexpressed and knocked out Srgap2 in murine osteosarcoma cell lines." (PMID 27966608, 2016). "This study evaluates the potential role of SRGAP2 in metastases-associated properties of osteosarcoma cell lines through Srgap2 knockout via the CRISPR/Cas9 nuclease system and conditional overexpression in the murine osteosarcoma cell lines K12 and K7M2." (PMID 27966608, 2016). "Metastatic samples had either 1.8 greater SRGAP2C: SRGAP2 transcript ratio (n = 2) or a two-fold reduction of ENAH compared to primary osteosarcoma samples (n = 5)." (PMID 27966608, 2016). "Mild to high immuoreactivity to anti-SRGAP2 antibody was observed in the periosteum of normal bone and in low-grade osteosarcoma samples." (PMID 27966608, 2016). "Here we functionally evaluate the potential role of SRGAP2 in osteosarcoma development and metastasis." (PMID 27966608, 2016). "The effects of Srgap2 expression modulation in the murine OS cell lines support the hypothesis that SRGAP2 may have a role as a suppressor of metastases in osteosarcoma." (PMID 27966608, 2016). "The insertion locations and the promoter direction of transposons within Srgap2 in the primary osteosarcoma tumors and metastatic nodules reveal a profile indicative of a tumor suppressor gene: the transposons are inserted throughout the gene without a bias in promoter orientation." (PMID 27966608, 2016). "The data presented here support our hypothesis that SRGAP2 may have a role as a suppressor of metastases in osteosarcoma." (PMID 27966608, 2016). "Then, they used CRISPR/Cas9 and doxycycline to knock out and overexpress SRGAP2 respectively in murine osteosarcoma cell lines, and found that SRGAP2 knockout increased cell migration, whereas SRGAP2 overexpression reduced cell migration, demonstrating that SRGAP2 may act as a migration inhibitor." (PMID 33546657, 2021). "In high-grade, stage II osteosarcoma samples, expression of SRGAP2 was substantially reduced or absent in over half of the samples (n = 19/36)." (PMID 27966608, 2016).
osteosarcoma (continued). "Additionally, SRGAP2 and other genes in the Slit-Robo pathway have altered transcript levels in a subset of mouse and human osteosarcoma, and SRGAP2 protein expression is reduced or absent in a subset of primary tumor samples." (PMID 27966608, 2016). "The murine osteosarcoma cell lines K12, created from a spontaneous tumor, and a highly metastatic derivative called K7M2, created through in vivo passaging, were used in this study22SRGAP2 overexpression was achieved with doxycycline inducible PiggyBac vectors containing human SRGAP2 cDNA." (PMID 27966608, 2016). "This study also found that SRGAP2, SRGAP2C, and other genes in the Slit-Robo pathway have altered transcript levels in a subset of mouse and human osteosarcoma, and SRGAP2 protein expression is reduced or absent in half of primary tumor samples." (PMID 27966608, 2016).
brain tumor (2 papers, 2021 to 2023). "For example, similar expression levels of NDRG1, LDHA, MHCII molecules, interferon genes, GPM6A, C9, and SRGAP2 were discovered in different myeloid subpopulations, indicating the similar functional states in different brain tumors." (PMID 38094301, 2023). "If the gene transcription control unit (i.e., the intergenic region of the two sub-gene units, SRGAP2 and FAM72) gets out of control, NSCs may transform into cancer stem cells and generate brain tumor cells responsible for brain cancer such as glioblastoma multiforme (GBM)." (PMID 33804473, 2021).
hepatocellular carcinoma (2 papers, 2022 to 2024). A malignant tumor that arises from hepatocytes. "In hepatocellular carcinoma, an elevated level of SRGAP2 is an indicator of a poor prognosis, while SRGAP2 silencing drastically mitigates cancer metastasis." (PMID 36277474, 2022).
Pancreatic Cancer (2 papers, 2022 to 2024). "Considered that ROBO1 plays a key role in angiogenesis, and we hypothesized that SRGAP2 and ROBO1 coregulate angiogenesis in pancreatic cancer." (PMID 36277474, 2022).
Arthritis (1 paper, 2023). Inflammation of a joint. "In this context, it has been reported that the elimination of endogenous expression of SRGAP2 promotes neurite growth in differentiated cells and contributes to the restriction of osteoclastogenesis during arthritis-related inflammation." (PMID 37936684, 2023).
ductal carcinoma (1 paper, 2023). "Immunochemistry of ductal carcinoma of breast showed that srGAP2 aggregation was more pronounced in “budding” cancer cells, which was invading into the surrounding basement membrane; srGAP2 expression was significantly increased in the invasive ductal carcinoma." (PMID 36593959, 2023).
infantile epileptic encephalopathy (1 paper, 2013). an epileptic condition characterized by epileptiform abnormalities associated with progressive cerebral dysfunction. "SRGAP2 has also recently been implicated in a severe neurodevelopmental syndrome causing early infantile epileptic encephalopathy and SRGAP2 knockout mice are prone to epileptic seizures." (PMID 23505444, 2013).
Intellectual disability (1 paper, 2020). "A microdeletion of 1q32.1, where the SRGAP2 gene is localized, causes Van der Woude syndrome accompanied with intellectual disabilities." (PMID 33425915, 2020). "The disruption of SRGAP2 expression was found in patients diagnosed with West syndrome, who demonstrate intellectual disability." (PMID 33425915, 2020).
Iron deficiency (1 paper, 2019). "Iron deficiency altered methylation at the genes regulating ephrin B signaling/ephrin receptor signaling (data not shown), including increased methylation at Ephb1, Itsn1, Prkar1b, and Srgap2, and decreased methylation at Arhgef15, Mknk1, and Slit3 loci." (PMID 31137889, 2019).
neuroblastoma (1 paper, 2013). Neuroblastoma (NB) is the most common solid, extracranial childhood tumor. "Thus, srGAP2 may also serve as a novel molecular target for human neuroblastoma therapy." (PMID 23505444, 2013).
oral cancer (1 paper, 2024). "Moreover, SCC15-specific upregulation was observed with KCNA4 and SRGAP2 and downregulation among SCC15 cells of FAM135A, which was observed among all other oral cancer cell lines." (PMID 38396844, 2024). "However, three miR-145 downstream targets were identified in the least chemotherapy-resistant cells, exhibiting the differential upregulation of KCNA4 and SRGAP2, as well as the downregulation of FAM135A, with this expression pattern not detected in any of the other oral cancer cell lines." (PMID 38396844, 2024).
schizophrenia (1 paper, 2013). A major psychotic disorder characterized by abnormalities in the perception or expression of reality. "The inverse F-BAR (IF-BAR) domain proteins srGAP1, srGAP2 and srGAP3 are implicated in neuronal development and may be linked to mental retardation, schizophrenia and seizure." (PMID 23505444, 2013).
triple-negative breast carcinoma (1 paper, 2023). An invasive breast carcinoma which is negative for expression of estrogen receptor (ER), progesterone receptor (PR), and human epidermal growth factor receptor 2 (HER2). "SrGAP2 exhibits tension gradients among different parts in the stiff-directionally migrating triple-negative breast cancer cells." (PMID 36593959, 2023). "We next investigated whether srGAP2 directly regulates Triple-Negative Breast Cancer (TNBC) cells invasion in vitro." (PMID 36593959, 2023).
uterine cancer (1 paper, 2021). Primary or metastatic malignant neoplasm involving the uterine corpus and/or the cervix. "Indeed, SRGAP2 itself shows no changes in its comparatively higher expression (with FAM72A) with slight differences in promoter methylation of SRGAP2 in breast, liver, lung, and uterine cancers." (PMID 33804473, 2021).
cancer (9 papers, 2016 to 2025). A tumor composed of atypical neoplastic, often pleomorphic cells that invade other tissues. "Lines of evidence demonstrate alternation of srGAP2 expression pattern closely associated with the cancer progression." (PMID 36593959, 2023). "Srgap2 was recurrently mutated in four Sleeping Beauty screens documented in the Candidate Cancer Gene Database, a database of cancer driver genes from Sleeping Beauty transposon based forward genetic screens in mice." (PMID 27966608, 2016). "The present study suggested that srGAP2 acts as a mechanotransduction protein across cell membrane and cytoskeleton, involved in malignant cell migration and cancer process." (PMID 36593959, 2023). "Therefore, our findings provide further evidence of a context-dependent role for SRGAP2 during cancer progression." (PMID 36277474, 2022). "Therefore, the dual function of SRGAP2 in cancer is supported by experimental evidence." (PMID 36277474, 2022). "These genes were presumably involved in cancer (SMG6, HCK), cellular growth (CPVL), reproduction (ADGB, CRISP1, CTTNBP2NL, WDR78), and nervous system (AUTS2, CNTNAP2, CPVL, SRGAP2)." (PMID 40149444, 2025). "The results showed that srGAP2 phosphorylation and SDC4-mediated PKCα recruitment were more obvious in cancer tissues compared with para tissues." (PMID 36593959, 2023). "SrGAP2 was phosphorylated on serine residue in TNBC tissues, which was hardly observed in para-cancer tissues." (PMID 36593959, 2023). "Targeting the srGAP2 phosphorylation and its mechanical transduction can develop therapeutic strategies of inhibiting TNBC cells durotaxis and new perspectives of the cancer treatment." (PMID 36593959, 2023). "Changes in expression may contribute to cancer metastasis, and the SRGAP2 protein is reduced or absent in many tumor samples." (PMID 35629083, 2022). "Comparing the corresponding methylation-expression statuses in SRGAP2 revealed that there is no clear difference in its methylation status, which correlates to no or minor changes in its expression status across the same cancer tissues." (PMID 33804473, 2021).
tumor (6 papers, 2016 to 2023). "These suggest the polarized srGAP2 tension necessary for fast movement of tumor cells in stiff-directed matrix." (PMID 36593959, 2023). "SRGAP2 is reported to be a tumor suppressor, and its expression is usually induced when FAM72 expression is blocked." (PMID 33804473, 2021). "Given the changes observed in Srgap2 expression in a subset of primary tumors, it is possible that SRGAP2 also plays a role in primary tumor growth and later in metastasis." (PMID 27966608, 2016). "We considered that cytoskeleton-dependent mechanical changes might be responsible for srGAP2 involved in tumor cell migration." (PMID 36593959, 2023). "Having demonstrated that exosomal miR-29b from PC cells downregulated ROBO1 and SRGAP2 expression in HUVECs, we investigated whether ROBO1 and SRGAP2 were necessary for suppression of tumor cell-induced angiogenesis by exosomal miR-29b." (PMID 36277474, 2022). "However, in non-neuronal cells, SRGAP2 expression is needed for rearranging the cytoskeleton required for cell-specific locomotion and motility and, if genomic rearranging occurs within the genomic SRGAP2 body, its tumor suppressor function is abolished, and metastasis is induced." (PMID 33804473, 2021). "Western Blot analysis of tumor tissue from the mice presented that, in GFP-srGAP2 + SDC4 KD group, srGAP2 phosphorylation level and PKCα membrane translocation were significantly decreased." (PMID 36593959, 2023). "In this study, an increased SRGAP2C: SRGAP2 transcript ratio or decreased expression of ENAH was found in all juvenile metastatic lesions (n = 7) compared to osteoblasts and primary tumor samples (n = 5)." (PMID 27966608, 2016).
infection (1 paper, 2023). The state of being infected such as from the introduction of a foreign agent such as serum, vaccine, antigenic substance or organism. "Similarly, a number of genes placed in “Axonal guidance”, including several modulated by infection (SLIT2, PLCD1, SLIT-ROBO Rho GTPase-activating protein 2 (SRGAP2) and TUBA4A), showed elevated expression." (PMID 37276213, 2023).
SRGAP2 also shares sentences with these, for which no sentence is quoted: Diabetic Nephropathy (4 papers); epilepsy (2); brain cancer (1); brain malformations (1); chronic myeloid leukemia (1); colorectal cancer (1); Epileptic encephalopathy (1); glioblastoma (1); Hyperglycemia (1); invasive ductal carcinoma (1); kidney diseases (1); psychiatric diseases (1).